IRF7 (interferon regulatory factor 7)
Diseases named in the same sentence as IRF7 in open-access papers (continued):
Sharing a sentence is not in itself a finding about the gene and the disease.
digestive tumours (1 paper, 2024). "Our analysis of PPI networks identified 11 hub genes (Myd88, Traf6, Irf7, Cdk4, Ccnd2, Mapkap1, Prr5, Mpp3, Serpinb6b and Pvrl3) that were implicated in digestive tumours." (PMID 38434966, 2024). "The PPI networks identified 10 hub genes that were implicated in digestive tumour immunotherapy target TIM-3 (Myd88, Traf6, Irf7, Cdk4, Ccnd2, Mapkap1, Prr5, Mpp3, Serpinb6b and Pvrl3)." (PMID 38434966, 2024).
myopathies (1 paper, 2023). "Using microarrays, IFIG expression levels (including ISG5, Mx1, OAS1, IFIT4, IFIT1, IFI44, OAS3, OAS2, IRF7, and IFI27) in muscle samples were higher in DM than in other inflammatory myopathies, such as inclusion body myositis, polymyositis, necrotizing myopathy, and myopathies with inflammation." (PMID 36979843, 2023).
psychiatric disorder (1 paper, 2022). A disorder characterized by behavioral and/or psychological abnormalities, often accompanied by physical symptoms. "Considerable evidence suggests that type I IFN is associated with psychiatric disorders, and that the production of type I IFNs as a result of TLR4 induced IRF3 activation and TLR7 induced IRF7 activation may be closely associated with IFN-mediated psychiatric disorders." (PMID 36325336, 2022).
renal disease (1 paper, 2023). "Irf3 deletions create a dramatic renal disease phenotype in infected mice due to the loss of the IRF3-dependent defense, including IFN-β, and the overexpression of Irf7 and IRF7-dependent gene networks." (PMID 38251349, 2023).
respiratory diseases (1 paper, 2025). "This seems to be the case, although IRF7 deficiency appears to preferentially underlie respiratory diseases." (PMID 39680367, 2025).
IRF7 also shares sentences with these, for which no sentence is quoted: rheumatoid arthritis (5 papers); experimental autoimmune encephalomyelitis (3); viral disease (3); alcohol dependence (2); astrocytoma (2); brain tumor (2); Emphysema (2); Hypertension (2); intrahepatic cholangiocarcinoma (2); liver cirrhosis (2); Pitt-Hopkins syndrome (2); promyelocytic leukemia (2); pulmonary fibrosis (2); septic shock (2); Wiskott-Aldrich syndrome (2); acute cystitis (1); acute lymphoblastic leukemia (1); acute monocyte leukemia (1); acute pancreatitis (1); adenocarcinoma (1); alcoholism (1); allergies (1); Alzheimer disease (1); arbovirus infection (1); autoimmune hepatitis (1); bacterial pneumonia (1); bare lymphocyte syndrome (1); bone metastasis (1); brain injury (1); bronchiectasis (1).
A further 64 diseases each share a sentence with IRF7 in 1 paper.